TPRA1 (transmembrane protein adipocyte associated 1)
Synonyms: GPR175; TMEM227; TPRA40; FLJ32197
Tractability: Antibody: UniProt predicts a signal peptide or a membrane-spanning region; its Gene Ontology location is reachable by antibodies, with medium confidence. PROTAC: ubiquitination databases record sites on it; its protein half-life has been measured.
Gene: Protein-coding gene on chromosome 3 (127,571,232 to 127,598,318, reverse strand). Ensembl gene ENSG00000163870.
Subcellular location: Membrane
Subcellular location (Human Protein Atlas): Vesicles
Gene Ontology:
Molecular function: protein binding; G protein-coupled receptor activity
Biological process: lipid metabolic process; G protein-coupled receptor signaling pathway
Cellular component: membrane
Genetic constraint (gnomAD): Loss-of-function variants: 28 observed, 40.93 expected, observed/expected ratio (o/e) 0.68, 90% interval 0.51 to 0.94. The upper end of that interval is the gene's LOEUF score, 0.94, which puts it in group 3 of 6, group 1 being the genes least tolerant of losing a copy. Missense variants: 441 observed, 491.19 expected, observed/expected ratio (o/e) 0.9, 90% interval 0.83 to 0.97. Synonymous variants: 219 observed, 213.06 expected, observed/expected ratio (o/e) 1.03, 90% interval 0.92 to 1.15.
Homologues: Orthologues: chimpanzee TPRA1 (99% identical), rabbit TPRA1 (92% identical), mouse Tpra1 (91% identical), rat Tpra1 (91% identical), guinea pig TPRA1 (90% identical), dog TPRA1 (86% identical), tropical clawed frog tpra1 (74% identical), zebrafish tpra1 (73% identical), macaque TPRA1 (64% identical), Caenorhabditis elegans tpra-1 (34% identical).
Diseases named in the same sentence as TPRA1 in open-access papers:
TPRA1 is named in the same sentence as 15 diseases in open-access papers, as found by Europe PMC text mining. Sharing a sentence is not in itself a finding about the gene and the disease. The quoted sentences say what the papers report.
bladder cancer (1 paper, 2025). "Conversely, ectopic expression of TPRA1 in bladder cancer UMUC3 cells, which showed less TPRA1 expression, rendered them more susceptible to OVM infection, and trans‐complementation of TPRA1 in 22Rv1ΔTPRA1 cells fully restored OVM infectivity." (PMID 41053536, 2025).
colon adenocarcinoma (1 paper, 2025). "Notably, TPRA1 is an unfavorable prognostic marker in colon adenocarcinoma and liver hepatocellular carcinoma, raising the possibility that its upregulation contributes to malignant transformation." (PMID 41053536, 2025).
colon cancer (1 paper, 2025). "To confirm the role of TPRA1 in OVM infection, we demonstrated that silencing TPRA1 in prostate cancer 22Rv1 cells and colon cancer SW620 cells using siRNA significantly reduced virus infection rate." (PMID 41053536, 2025).
endometriosis (1 paper, 2025). The growth of functional endometrial tissue in anatomic sites outside the uterine body. "Studies have demonstrated that TPRA1 and TPRV1 expressions are higher in the ectopic endometrial tissue of endometriosis patients, and this elevation is significantly associated with endometriosis-related pain." (PMID 40004233, 2025).
lung carcinoma (1 paper, 2025). "Similarly, CRISPR‐Cas9‐mediated disruption of TPRA1 in 22Rv1 and lung cancer PC‐9 cells resulted in a substantial decrease in OVM infection." (PMID 41053536, 2025).
viral infection (1 paper, 2025). "In summary, we identify TPRA1 as a novel receptor for OVM, mediating viral infection and amplifying its oncolytic efficacy." (PMID 41053536, 2025). "In this study, we identify TPRA1 as a novel receptor for OVM, essential for mediating viral infection and amplifying its antitumor efficacy." (PMID 41053536, 2025).
cancer (2 papers, 2022 to 2025). A tumor composed of atypical neoplastic, often pleomorphic cells that invade other tissues. "In particular, we found that TPRA1 exhibited the highest mutation frequency (6%) across cancer types." (PMID 35614079, 2022). "Genetic alterations were correlated with transcriptome dysregulation of TRP genes, and we found that TRPM2, TRPM8, and TPRA1 showed extent dysregulation in cancer." (PMID 35614079, 2022). "Ectopic expression of TPRA1 in UMUC3 cells significantly enhanced OVM replication and subsequent cancer cell death." (PMID 41053536, 2025). "Analyses of tumor tissue microarrays and TCGA data reveal frequent TPRA1 upregulation in malignancies, suggesting broad applicability for OVM in diverse cancers." (PMID 41053536, 2025). "TPRA1 is a member of the G protein‐coupled receptor (GPCR) family, a class of proteins with well‐documented roles in cancer biology, including tumor growth, metastasis, immune evasion, and therapy resistance." (PMID 41053536, 2025). "Extracellular region of TPRA1 directly binds OVM particles via glycosylation, while its cytoplasmic tail mediates virus endocytosis, collectively enabling efficient viral entry and cancer cell lysis." (PMID 41053536, 2025).
infection (1 paper, 2025). The state of being infected such as from the introduction of a foreign agent such as serum, vaccine, antigenic substance or organism. "In this study, we employed a membrane protein‐targeted CRISPR‐Cas9 screen to identify transmembrane protein adipocyte‐associated 1 (TPRA1) as a critical factor for OVM infection." (PMID 41053536, 2025). "Notably, ΔC‐tail expressed in cells exhibited a deficiency in mediating OVM internalization and infection compared to wild‐type TPRA1." (PMID 41053536, 2025). "Cells expressing TPRA1 with both mutations (N11/23Q) showed significantly reduced OVM binding and lower infection rates compared to those expressing wild‐type TPRA1." (PMID 41053536, 2025). "Mechanistically, TPRA1 facilitates OVM infection by promoting both viral attachment and internalization." (PMID 41053536, 2025). "To investigate the mechanism by which TPRA1 enhances OVM infection, we first conducted a plaque formation‐based entry assay, and significantly more plaques were observed in TPRA1‐overexpressing UMUC3 cells." (PMID 41053536, 2025). "By overexpressing these genes in HEK293 cells, we found that TPRA1 most potently enhances OVM infection." (PMID 41053536, 2025). "To assess whether TPRA1‐mediated enhancement of OVM infection results in increased viral replication and oncolytic activity, we first measured virus titers and cell viability in vitro." (PMID 41053536, 2025). "To further explore the molecular mechanism of TPRA1‐mediated OVM entry, we used Arbidol, a clathrin‐dependent endocytosis inhibitor, and found that Arbidol can partially inhibit the infection of OVM, suggesting TPRA1‐mediated entry via the clathrin pathway." (PMID 41053536, 2025).
renal disease (1 paper, 2021). "In renal disease, TPRA1 plays different roles in different cell types accordingly." (PMID 33810314, 2021).
tumor (1 paper, 2025). "OVM's oncolytic efficacy correlated strongly with TPRA1 expression levels in tumor tissues, further confirming TPRA1 as a predictive biomarker for OVM therapeutic response." (PMID 41053536, 2025). "Consistently, UMUC3 tumors overexpressing TPRA1 exhibited significantly higher OVM abundance in the tumor tissue, whereas PC‐9 tumors with TPRA1 knockout showed reduced OVM abundance compared to vector controls." (PMID 41053536, 2025). "Additionally, in multiple solid tumor‐bearing mouse models, TPRA1 protein expression in tumors positively correlates with the OVM‐induced tumor growth suppression." (PMID 41053536, 2025). "A large proportion of tumor tissues showed high levels of TPRA1, suggesting that OVM could be an effective therapeutic agent for these patients." (PMID 41053536, 2025). "In contrast, in the PC‐9 tumor model, the therapeutic efficacy of OVM was abolished upon TPRA1 knockout." (PMID 41053536, 2025). "We establish TPRA1 as a novel receptor for OVM, significantly boosting its anti‐tumor efficacy both in vitro and in vivo." (PMID 41053536, 2025). "Mechanistically, the N‐glycosylated ectodomain of TPRA1 directly binds to OVM particles, while its intracellular C‐tail orchestrates endocytic trafficking to the early endosome, collectively driving viral entry into tumor cells." (PMID 41053536, 2025). "Importantly, TPRA1 expression correlates positively with OVM sensitivity across preclinical models and patient‐derived tumor samples, underscoring its clinical relevance." (PMID 41053536, 2025). "Our findings demonstrate that TPRA1 interacts with OVM particles via its ectodomain, while its intracellular C‐terminal domain facilitates OVM internalization, thereby enhancing viral entry into tumor cells." (PMID 41053536, 2025).
TPRA1 also shares sentences with these, for which no sentence is quoted: asthma (1 paper); bladder urothelial carcinoma (1); lung adenocarcinoma (1); prostate adenocarcinoma (1); prostate carcinoma (1).